BST2 (bone marrow stromal cell antigen 2)
Diseases named in the same sentence as BST2 in open-access papers (continued):
Sharing a sentence is not in itself a finding about the gene and the disease.
colon cancer (5 papers, 2021 to 2025). "According to the GSEA results, the overexpression of BST2 was significantly correlated with the immune response in the tumor microenvironment in colon cancer." (PMID 36594082, 2023). "GO molecular function analysis demonstrated that immune-related pathways such as cytokine binding and immune receptor activity were correlated with BST2-high colon cancers." (PMID 36594082, 2023). "For the pathways annotated by KEGG analysis, some signaling pathways, such as cytokine receptor interaction, cell adhesion molecules CAMs, ECM receptor interaction and focal adhesion, were significantly enriched in high-BST2 colon cancer." (PMID 36594082, 2023). "Moreover, the prognostic significance of BST2 in colon cancer has been put forward as early as 2015." (PMID 35237578, 2022). "This included PPP1R14D, BST2 and ZNF550, whose expression was induced by 5-aza-2′-deoxycytidine (decitabine) treatment in colon cancer cell lines with low basal expression and high promoter methylation of these genes." (PMID 33892786, 2021). "Similar results were found that elevated BST2 level, HOXC6, and TNNT1 level are correlated with poor prognosis in colon cancer patients, while TNNT1 protein may be mediated through the process of epithelial–mesenchymal transition." (PMID 34381786, 2021).
endometriosis (5 papers, 2023 to 2025). The growth of functional endometrial tissue in anatomic sites outside the uterine body. "In light of this background, the current study aimed to investigate the molecular mechanisms underlying lymphangiogenesis in endometriosis by which NF-κB signaling is activated by BST2." (PMID 37143676, 2023). "Although the intracellular signaling of BST2 is still unclear, further understanding of the mechanisms underlying the functions regulated by BST2 may shed light on novel therapeutic targets for endometriosis." (PMID 37143676, 2023). "Using machine learning algorithms, five key genes were selected in the endometriosis: BST2, IL4R, INHBA, PTGER2, and MET." (PMID 40405976, 2025). "In brief, based on the function of immune cells and corresponding factors recruited by new lymphatic vessels, it is reasonable to conclude that BST2-mediated immune regulation can contribute to the development of endometriosis." (PMID 37143676, 2023). "To investigate the potential biological behavior of BST2 in endometriosis, we took advantage of a series of papers in PubMed." (PMID 37143676, 2023). "The xenograft model demonstrated that the volume and weight of endometriosis in the BST2-knockdown group (n=5) was significantly lower than in the control group (n=5)." (PMID 37143676, 2023). "Taken together, our findings provide novel insight into the mechanism by which BST2 participates in a feedback loop with the NF‐κB signaling pathway and reveal a novel biomarker and potential therapeutic target for endometriosis." (PMID 37143676, 2023). "Combined with our in vitro and in vivo results, we have strong reasons to conclude that BST2 generates favorable conditions for the progression of endometriosis." (PMID 37143676, 2023). "In summary, our studies showed that BST2-induced NF-κB activation played a vital role in the development and progression of endometriosis." (PMID 37143676, 2023). "From a functional point of view, our results indeed suggest that BST2 can regulate cell proliferation, migration, and apoptosis in a cell culture system, as well as partially in a mouse model of endometriosis." (PMID 37143676, 2023). "IRF6 regulates the high expression of BST2, which further activates the NF-κB signaling pathway to induce proliferation, migration, apoptosis and lymphangiogenesis in endometriosis." (PMID 37143676, 2023). "To determine the effect of BST2 on the development of endometriosis lesions, we conducted further experiments to validate the characteristics of BST2 using a mouse model." (PMID 37143676, 2023). "Collectively, BST2 contributes to endometriosis lesion growth and lymphangiogenesis in vivo." (PMID 37143676, 2023). "Based on our previous studies and the JASPAR software analysis, we hypothesize that the transcription factor IRF6 may regulate BST2 expression in endometriosis by directly binding to its promoter region." (PMID 37143676, 2023). "Overall, the data presented in this study reveal the transcription factor IRF6-associated regulation of BST2 expression, the pathological function of BST2 in endometriosis, novel signaling pathway mediated by BST2, and the therapeutic potential of targeting BST2 for the treatment of endometriosis." (PMID 37143676, 2023). "When the expression level of BST2 is reduced, it means that the binding to NF-κB pathway is decreased, which in turn weakens the activation of this pathway and lessen the effect of NF-κB on the biological behavior of endometriosis." (PMID 37143676, 2023). "Moreover, an increase in BST2 was also observed in EESCs compared to control cells, suggesting that BST2 may be involved in the development and pathogenesis of endometriosis." (PMID 37143676, 2023). "Based on these outcomes, we can infer that BST2 can regulate the transcription of VEGFC via the NF-κB signaling pathway, thereby promoting lymphangiogenesis in endometriosis." (PMID 37143676, 2023).
endometriosis (continued). "It is anticipated that targeting BST2 could be an alternative, non-hormonal treatment for endometriosis in the future." (PMID 37143676, 2023).
glioma (5 papers, 2020 to 2025). A benign or malignant brain and spinal cord tumor that arises from glial cells (astrocytes, oligodendrocytes, ependymal cells). "We next examined the expression of BST2 based on tumor grade and molecular characteristics of glioma histological and molecular subtypes." (PMID 35865015, 2022). "In GBM, the expression of BST2 was negatively correlated with CD8+ T cells (correlation coefficient −0.152), while the expression of BST2 in low grade glioma was positively correlated with CD8+ T cells (correlation coefficient 0.226)." (PMID 35865015, 2022). "We found the gene to be associated with other immune checkpoint genes, which highlights BST2 as another molecular target for immunotherapy tailored for human gliomas." (PMID 35865015, 2022). "Functional validation experiments demonstrated that the knockdown of BST2 or DIRAS3 expression in glioma cells significantly suppresses their in vitro migration and invasion capabilities, confirming their critical regulatory roles in malignant phenotypic progression." (PMID 40649981, 2025). "BST2 expression increases in the malignant cells of glioma during tumor progression." (PMID 33193404, 2020). "Given their evolutionarily conserved immunoregulatory functions across solid tumors, BST2 and DIRAS3 emerge as novel biomarkers for glioma immunotherapy." (PMID 40649981, 2025). "Integrating prior research with our current findings, we establish BST2 and DIRAS3 as key regulatory genes governing T-cell-mediated immune evasion in glioma." (PMID 40649981, 2025). "This study expands upon our previous findings about the roles of BST2 and DIRAS3 in the evasion of the glioma immune milieu by examining their direct regulatory effects on tumor cell invasion and migratory capabilities." (PMID 40649981, 2025). "We found that BST2 was negatively correlated with tumor purity in GBM and low grade gliomas and (correlation coefficients −0.196 and −0.353)." (PMID 35865015, 2022). "Future research should focus on validating these hypotheses and exploring the therapeutic potential of targeting BST2 and DIRAS3 in glioma treatment." (PMID 40649981, 2025).
influenza (5 papers, 2016 to 2025). An acute viral infection of the respiratory tract, occurring in isolated cases, in epidemics, or in pandemics; it is caused by serologically different strains of viruses (influenzaviruses) designated A, B, and C, has a 3-day incubation period, and usually lasts for 3 to 10 days. "To further investigate the role BST2 in infectious diseases, we conducted an influenza vaccination experiment using dendritic cells to assess its impact on antigen presentation." (PMID 39796009, 2024). "Mice receiving influenza antigens via BST2+/+ DCs exhibited higher levels of anti-influenza-specific immunoglobulins in serum and less severe disease after virus challenge compared to mice receiving BST2−/− DCs loaded with influenza antigen." (PMID 39796009, 2024). "Additionally, an IFNγ-based enzyme-linked immunospot (ELISPOT) assay revealed more IFNγ-expressing cells in the Bst2+/+ DC-vaccinated group than in the Bst2−/− DC-vaccinated group upon stimulation with influenza-infected antigen-presenting cells." (PMID 39796009, 2024). "Notably, mice administered the influenza vaccine via Bst2−/− cDCs exhibited substantially inefficient virus clearance compared to mice administered the Bst2+/+ cDCs vaccine." (PMID 39796009, 2024). "Influenza, a respiratory illness like SARS-CoV-1 and -2, was expected to lead to differential expression of BST2, IFITM1, and ZBP1." (PMID 39874350, 2025). "A separate group found that BST2 is involved in suppressing SARS-CoV-2 replication in vitro, and ZBP1 can decrease the replication of SARS-CoV-1, SARS-CoV-2, influenza, and other viruses." (PMID 39874350, 2025). "Next, we assessed the cytotoxic activity of stimulated splenocytes against influenza-infected EL4 target cells and observed stronger cytotoxicity from the Bst2+/+ DC-vaccinated group compared to the Bst2−/− DC-vaccinated group." (PMID 39796009, 2024). "The lncRNAs BST2 and BST2 share the same promoter and are co-expressed upon IFN stimulation or influenza infection to promote the expression of the antiviral protein ISG BST2/tetherin." (PMID 36560611, 2022).
lung adenocarcinoma (4 papers, 2016 to 2026). A carcinoma that arises from the lung and is characterized by the presence of malignant glandular epithelial cells. "Overall, our data reveal an important physiological role for S100-A15 in comprehending the proliferative, metastatic, and invasive properties of lung adenocarcinoma which may be orchestrated by CTNNB1 with the involvement of ZEB1, CDC42, HSP90AA1, PCNA and BST2." (PMID 28498804, 2017).
nasopharyngeal carcinoma (4 papers, 2017 to 2024). A carcinoma arising from the nasopharyngeal epithelium. "Cisplatin-sensitive nasopharyngeal carcinoma cells showed downregulation of BST2 expression and were more susceptible to apoptosis." (PMID 38753689, 2024).
atherosclerosis (3 papers, 2017 to 2024). A disease characterized by the build-up of fatty material and calcium deposition in the arterial wall resulting in partial or complete occlusion of the arterial lumen.
brain tumor (3 papers, 2016 to 2022). "SMOC1, a SPARC-related ligand overexpressed in brain tumors, recovered BST2, IGSF23, and SMOC2 as the highest-ranking hits." (PMID 36178190, 2022). "Finally, the expression of BST2 was found to be increased during brain tumor progression in an orthotopic mouse tumor model where it was mainly located in the cell membrane and cytoplasm." (PMID 35865015, 2022). "However, BST2 silencing and immunotherapy did not improve the overall survival of tumor bearing mice in an orthotopic mouse brain tumor model." (PMID 35865015, 2022).
head and neck squamous cell carcinoma (3 papers, 2019 to 2023). A squamous cell carcinoma that arises from any of the following anatomic sites: lip and oral cavity, nasal cavity, paranasal sinuses, pharynx, larynx, and salivary glands. "Relevantly, CD317 (also known as BST2) antibodies have been recently tested for in vivo depletion of pDCs in an immunocompetent transgenic mouse model of head and neck squamous cell carcinoma (HNSCC)." (PMID 32054102, 2020).
metastatic tumors (3 papers, 2014 to 2016). "Meta-analysis of TCGA (BRCA) human data that showed that BST-2 is most significantly associated with luminal B tumors, invasive ductal carcinoma, and metastatic tumors imply that BST-2 in cancer cells could be a prognostic factor for highly aggressive cancers." (PMID 25499888, 2014). "Additionally, analysis of BST-2 expression profile with TCGA dataset segregated into normal, primary tumor, and metastatic tumor revealed that levels of BST-2 in metastatic tumors were highly elevated compared to primary tumors." (PMID 25499888, 2014). "Moreover, metastatic tumors expressed more BST-2 than primary tumors." (PMID 25499888, 2014).
multiple sclerosis (3 papers, 2013 to 2026). A progressive autoimmune disorder affecting the central nervous system resulting in demyelination. "This sensory‐specific role meaningfully extends BST2's established functions: while its dysregulation exacerbates neuroinflammation in Alzheimer's disease and multiple sclerosis, we demonstrate SC‐autonomous regulation of migratory function." (PMID 41391004, 2026). "Furthermore, BST2 expression is also upregulated in demyelinating diseases such as multiple sclerosis (MS) and experimental autoimmune encephalomyelitis (EAE)." (PMID 41391004, 2026). "Strikingly, polymorphisms in TRIM5, TRIM22, and BST2, but not APOBECs or TREX1 were significantly associated to another neuroinflammatory disorder, multiple sclerosis." (PMID 29872426, 2018).
oral cavity cancer (3 papers, 2015 to 2024). A primary or metastatic malignant neoplasm involving the oral cavity. "Upregulation of BST2 indicates nodal metastasis and a bad prognosis in oral cavity cancer." (PMID 34692852, 2021).
rheumatoid arthritis (3 papers, 2015 to 2022). A chronic, systemic autoimmune disorder characterized by inflammation in the synovial membranes and articular surfaces. "BST2 (bone marrow stromal cell antigen 2) encodes a protein that may play a role in pre-B cell growth and in rheumatoid arthritis." (PMID 35308143, 2022).
amyotrophic lateral sclerosis (2 papers, 2024 to 2026). Amyotrophic lateral sclerosis (ALS) is a neurodegenerative disease characterized by progressive muscular paralysis reflecting degeneration of motor neurons in the primary motor cortex, corticospinal tracts, brainstem and spinal cord. "Expression of BST2 in microglia is significantly increased during the development of ALS (amyotrophic lateral sclerosis)." (PMID 38890712, 2024). "Elevated BST2 expression also occurs in amyotrophic lateral sclerosis (ALS)." (PMID 41391004, 2026).
astrocytoma (2 papers, 2013 to 2016). "Bone marrow stromal cell antigen 2 (BST2) has been identified as a tumor marker for astrocytomas, and was first described as a marker for B-cell maturation." (PMID 24137217, 2013). "BST2 expression is upregulated in high grade human astrocytoma." (PMID 27344170, 2016).
Autoimmunity (2 papers, 2015 to 2022). The occurrence of an immune reaction against the organism's own cells or tissues. "Regarding the bi-directional role of BST2 in immunoregulation, we speculate that it is a protective measure of the host immune system to prevent overactive autoimmunity, rather than viruses utilizing BST2 to reduce immune activation to escape the host immune response." (PMID 36176574, 2022).
B cell lymphoma (2 papers, 2013 to 2022). "In fact in B-cell lymphoma, targeting BST2 with two independent monoclonal antibodies delayed tumor growth in a syngeneic mouse model of the disease." (PMID 35865015, 2022).
bladder cancer (2 papers, 2020 to 2022). "Studies showed that silencing of BST2 with siRNA inhibits the phosphorylation of AKT and ERK1/2 in bladder cancer cells." (PMID 31957537, 2020).
Dengue (2 papers, 2023). "Expression of BISPR, OASL, and BST2 were upregulated during acute Dengue and Zika infection, similarly to what we observed in acute Chikungunya infection." (PMID 37922302, 2023).
diabetes (2 papers, 2020 to 2021). "However, comparable levels of PECAM1, CXCR2, SLC2A3, BST2, S100A11, S100A12, and CPNE3 were found in neutrophils from diabetes patients and controls (P > 0.05)." (PMID 32377527, 2020).
encephalitis (2 papers, 2017 to 2022). An acute inflammatory process affecting the brain parenchyma. "Although disease progression was faster in SARS-CoV-2 infected mice, infection with both viruses resulted in neuronal infection and encephalitis with increased expression of Interferon-stimulated Irf7, Bst2, Ifi294, as well as CxCL10, CCL5, CLC2, and LILRB4, and both models were uniformly lethal." (PMID 35967447, 2022).
HCMV infection (2 papers, 2011 to 2020). "To determine whether there was a causative relationship between AD169 entry and BST2 levels we knocked down BST2 mRNA levels with siRNA prior to PMA treatment and HCMV infection." (PMID 22072961, 2011). "Moreover, treatment of primary human monocytes with siRNA to BST2 reduced HCMV infection, suggesting that BST2 facilitates entry of HCMV into cells expressing high levels of BST2 either constitutively or in response to exogenous stimuli." (PMID 22072961, 2011). "In contrast to other enveloped viruses, we observed that BST2 increased HCMV infection." (PMID 22072961, 2011). "Taken together, above experiments suggest that increased BST2 levels enhance HCMV entry and that this facilitated entry might play an important role in HCMV infection of monocytes." (PMID 22072961, 2011). "However, the presence of BST2 is not sufficient for HCMV infection of other BST2-expressing cell types such as T cells and B cells, because HCMV replication can be also restricted post-entry (as observed for AD169 in THP-1 cells)." (PMID 22072961, 2011).
interstitial lung disease (2 papers, 2016 to 2020). A diverse group of lung diseases that affect the lung parenchyma. "A number of genes, such as Bst2, Rsad2, Ifi44, Oas2 and Stat2, were previously found to be downregulated in pulmonary fibroblasts from IPF patients and from scleroderma-associated interstitial lung disease." (PMID 27428020, 2016).
invasive breast carcinoma (2 papers, 2013 to 2018). A carcinoma that infiltrates the breast parenchyma. "Here, we show that BST-2 is linked to poor survival in invasive breast cancer patients as its expression positively correlates with disease severity." (PMID 30514852, 2018). "Using tumors from an invasive breast cancer (IBC) patient cohort, we found higher BST-2 levels in tumors that progressed beyond a localized state." (PMID 30514852, 2018).
lymphoma (2 papers, 2019 to 2020). A malignant (clonal) proliferation of B- lymphocytes or T- lymphocytes which involves the lymph nodes, bone marrow and/or extranodal sites. "In addition, monoclonal antibodies against BST2 possess significant antitumor activity in lymphoma and endometrial cancers." (PMID 30655550, 2019).
skin cancer (2 papers, 2023 to 2025). "Of the five MOBILE-hypothesized connector genes (BST2, CLIC2, FAM83D, ACSL5, and HIST2H2AA3) between IRF1 and PD-L1, BST2 was recently recognized as part of an immune/tumor-related signature that is significantly associated with the overall survival of skin cancer patients." (PMID 37414767, 2023). "Consistently, we observed inflammatory genes, including Ifng, Stat1, Ifit2, Ifit3, Isg15, and Bst2, being highly expressed in the T cell cluster in skin tumors." (PMID 40282557, 2025).
triple-negative breast carcinoma (2 papers, 2017). An invasive breast carcinoma which is negative for expression of estrogen receptor (ER), progesterone receptor (PR), and human epidermal growth factor receptor 2 (HER2). "Similar observation was made with MDA-MB-231 human triple negative breast cancer cell line that contains high levels of endogenous BST-2." (PMID 29299143, 2017).